PRLH (prolactin releasing hormone)
Description:
Stimulates prolactin (PRL) release and regulates the expression of prolactin through its receptor GPR10. May stimulate lactotrophs directly to secrete PRL.
Synonyms: PrRP; PRH
Tractability: Antibody: its Gene Ontology location is reachable by antibodies, with high confidence; UniProt places it where antibodies can reach, with medium confidence; UniProt predicts a signal peptide or a membrane-spanning region.
Target class: Secreted protein
Gene: Protein-coding gene on chromosome 2 (237,559,555 to 237,567,288, forward strand). Ensembl gene ENSG00000071677.
Subcellular location: Secreted
Pathways (Reactome):
Signal Transduction: Peptide ligand-binding receptors
Gene Ontology:
Molecular function: hormone activity; neuropeptide hormone activity; prolactin-releasing peptide receptor binding
Biological process: feeding behavior; G protein-coupled receptor signaling pathway; response to peptide hormone
Cellular component: extracellular region; cytoplasm
Genetic constraint (gnomAD): Loss-of-function variants: 7 observed, 3.86 expected, observed/expected ratio (o/e) 1.81, 90% interval 0.9 to 1.95. That is too few expected variants to judge how well the gene tolerates losing a copy. Missense variants: 145 observed, 113.21 expected, observed/expected ratio (o/e) 1.28, 90% interval 1.12 to 1.47. Synonymous variants: 65 observed, 46.04 expected, observed/expected ratio (o/e) 1.41, 90% interval 1.15 to 1.73.
Homologues: Orthologues: chimpanzee PRLH (100% identical), macaque PRLH (92% identical), rabbit PRLH (76% identical), mouse Prlh (69% identical), dog PRLH (68% identical), rat Prlh (63% identical), guinea pig PRLH (57% identical), tropical clawed frog prlh (30% identical), zebrafish prlh2 (30% identical).
Diseases named in the same sentence as PRLH in open-access papers:
PRLH is named in the same sentence as 22 diseases in open-access papers, as found by Europe PMC text mining. Sharing a sentence is not in itself a finding about the gene and the disease. The quoted sentences say what the papers report.
Obesity (26 papers, 2013 to 2025). Accumulation of substantial excess body fat. "PRLHR encodes a transmembrane protein for the prolactin-releasing hormone and has previously been associated with body weight control and obesity." (PMID 28814982, 2017).
prostate carcinoma (1 paper, 2013). A carcinoma that arises from epithelial cells of the prostate gland. "We haphazardly selected 4 PRLH-stained tissue sections from the 22 available prostate cancer tissue sections." (PMID 23342084, 2013). "PRLH staining was negligible in the 4 selected prostate cancer samples and the 2 available normal prostate samples, consistent with its selection as a negative control." (PMID 23342084, 2013).
cancer (4 papers, 2020 to 2023). A tumor composed of atypical neoplastic, often pleomorphic cells that invade other tissues. "Furthermore, the contribution of GNRH2, PRLH, GPR156, GRIK5, LHB, and CRHR2 to the neuroactive ligand-receptor interaction pathway are specified in ATLL in consistent with some other cancers." (PMID 34446027, 2021).
PRLH also shares sentences with these, for which no sentence is quoted: Anorexia (4 papers); depression (3); type 2 diabetes mellitus (3); Anxiety (2); Glucose intolerance (2); metabolic syndrome (2); amyloidosis (1); breast carcinoma (1); Cognitive impairment (1); endometrial cancer (1); Galactorrhea (1); Hypernatremia (1); Hypertension (1); mental disorder (1); neuroblastoma (1); neurodegenerative disease (1); pituitary tumor (1); steatosis (1); tumor (1).